USP28 (ubiquitin specific peptidase 28)
Diseases named in the same sentence as USP28 in open-access papers (continued):
Sharing a sentence is not in itself a finding about the gene and the disease.
tumor (continued). "In addition to maintaining the epithelial identity and promoting tumor growth through ΔNp63 protein stabilization, USP28 oncogenic activity might also be related to other signaling pathways." (PMID 32560247, 2020). "The hypothesis of USP28 as an oncogenic regulator in CLL is additionally supported by our observation that NOTCH1 signaling is not upregulated in CLL cells with del(11q) as it would have been expected in a simplistic model of the tumor suppressor mechanism in 11q." (PMID 40456839, 2025). "Previous studies have shown that USP28 modulates the SREBP2 and mevalonate pathways, promoting tumor growth in LUSC." (PMID 40853920, 2025). "As a tumor-suppressive decoy, FBXW-185aa inhibits USP28’s binding to FBXW7α, thus antagonizing the USP28-induced c-Myc stabilization." (PMID 39452835, 2024). "Some of these ubiquitination events are opposed by the activity of the deubiquitinase (DUB) USP28; for example, c‐MYC stability in human tumour cells is USP28 dependent and USP28 binds to MYC through a nuclear interaction with FBW7α." (PMID 37866880, 2024). "We next compared tumours from the SCC and ADC subtypes, as determined by keratin 5 (Krt5), thyroid transcription factor 1 (Ttf-1/Nkx2-1) and Usp28 staining, in KPL mice." (PMID 37202505, 2023). "In this model, deletion of Usp28 prevented LSCC formation, resulting in a reduced tumour load and enhanced survival." (PMID 37202505, 2023). "The knockdown of USP28 blunts the upregulation of PIM1 in xenograft tumor models and results in reduced tumor growth." (PMID 35326457, 2022). "The deubiquitinase USP28 was shown to bind c-Myc through an interaction with FBW7 ubiquitin ligase, a tumor suppressor, leading to c-Myc stabilization and tumor cell proliferation." (PMID 33572615, 2021). "Small tumour lesions were excised from treated animals and the DUB activity assessed using ubiquitin‐suicide probes, followed by immunoblotting against USP28 (Fig EV5B and C)." (PMID 32128997, 2020). "We show that depletion of the DUBs USP28 and BRCC3 induces positive proliferation phenotypes, suggesting that they have tumor suppressive functions." (PMID 30838976, 2019). "USP28 interacts and deubiquitylates LSD1, and the expression levels of the two proteins correlate well in tumor cell lines and tumor samples." (PMID 27516771, 2016). "Importantly, inhibition of USP28 sensitizes H1975/OSI cells to OSI therapy and thus reduces tumor burden in H1975/OSI xenograft models." (PMID 40855785, 2026). "USP28 inhibitors, such as FT206 and vismodegib, destabilize oncogenic substrates (e.g., c‐Myc, HIF1α) by blocking USP2's deubiquitinase activity, thereby suppressing tumor growth." (PMID 40855785, 2026). "USP28 interacts with c‐MYC through FBW7α and stabilizes c‐MYC in human tumor cells." (PMID 40227962, 2025). "USP28 loss in FBXW7-deficient mice slows proliferation, restores differentiation, and partially reverses tumorigenesis, showing USP28 promotes tumor growth without FBXW7." (PMID 41373479, 2025). "In addition to demonstrating excellent pharmacokinetic properties and potent anti-tumor effects, another advantage of FT206 is its significantly higher selectivity for USP28 over USP25." (PMID 40240356, 2025). "Furthermore, USP28 and LSD1 were both higher in cells isolated from a tumor model which contributes to the expansion of mammary stem cells." (PMID 36879346, 2023). "The results indicated that compared with siRNA of negative control (si-NC), the silence of USP28 significantly suppressed cell growth, and the formation of tumor cell colonies." (PMID 35299740, 2022).
tumor (continued). "Already in early‐stage lung primary tumours, Usp28 was overexpressed when compared to nontransformed tissue." (PMID 35364627, 2022). "Previous studies have described the recruitment of USP28 by the E3 ubiquitin ligases kelch-like family member 2 (KLHL2) and ring finger and CHY zinc finger domain containing 1 (RCHY1), but little is known about how these factors are affected by tumor hypoxia." (PMID 35326457, 2022). "In addition, five other genes, including TBPL1, USP28, NRG3, PPM1L, and RGR, were regulated by eRNAs expressed only in LGG tumor tissue; whereas SEMA4G was regulated by LGG-specific seRNAs." (PMID 35299740, 2022). "USP28 stabilizes the ∆Np63 protein and is required for SCC tumor maintenance." (PMID 34611298, 2022). "Irrespective of oncogenic driver, interference with USP28 abundance or activity suppressed tumour cell growth and survival of transformed lung cells in vitro and in vivo." (PMID 35364627, 2022). "USP28 behaves as a non-oncogene addiction gene, since wild type cells tolerate its inactivation, while tumor cells, SCC in particular, depend on its expression." (PMID 34611298, 2022). "Irrespective of oncogenic driver, tumour cells upregulate USP28, which stabilizes proto‐oncogenes, such as c‐MYC, c‐JUN or NOTCH." (PMID 35364627, 2022). "In addition, USP28 stabilizes ZNF304 leading to the hypermethylation and transcriptional silencing of tumor-suppressor genes upon oncogenic transformation." (PMID 34685632, 2021). "Moreover, we subcutaneously implanted PC cells with either USP28 single-knockdown or USP28 knockdown with FOXM1 overexpression into nude mice and monitored their tumour growth." (PMID 34584067, 2021). "USP28 was not only required for tumour induction, but also crucial for tumour maintenance, since upon USP28 depletion established SCC tumour cells completely failed to establish tumours in a syngeneic orthotopic transplantation experiment." (PMID 32128997, 2020). "To determine whether USP28 regulates genes involved in epithelial cell identity and SCC tumour formation via ∆Np63, we tested whether ectopic expression of ∆Np63 restores the expression of these genes in USP28‐depleted cells." (PMID 32128997, 2020). "In contrast, mice transplanted with USP28‐depleted cells failed to develop tumours, as only tumour‐free lungs were observed." (PMID 32128997, 2020). "Additionally, immunohistochemical staining of xenograft tumor tissues revealed reduced USP28 and MAST1 expression in the USP28-KO tumors compared with the mock control xenograft tumor tissues, while the expressions of USP28 and MAST1 were regained by reconstitution with USP28 or MAST1." (PMID 38498222, 2024). "Moreover, several DUBs, such as USP28 and USP8, have been reported to regulate hypoxia-inducible factor proteins, the key mediators in maintaining multiple CSC populations under the hypoxic tumor microenvironment." (PMID 38517383, 2024). "Interestingly, USP28 counteracts the activity of the F-box and WD repeat domain containing protein 7 (FBXW7), a tumour suppressor protein that is part of the SCF (Skp1, Cullin-1, F-box) protein complex and facilitates the ubiquitination and destabilisation of MYC among other proteins." (PMID 37202505, 2023). "Thus, during past investigations concerning the relationship between USP28 and tumor prognosis, the negative role of USP28 in prognosis has been discussed dominantly, while the positive role has also attracted scientists’ attention." (PMID 36879346, 2023). "Furthermore, USP28 upregulation is a common feature of tumour cells, irrespective of histological or molecular tumour subtype." (PMID 35364627, 2022). "However, to date, no studies have demonstrated that USP28 stabilizes the tumor suppressors Tp73 or Tap63." (PMID 34685632, 2021).
tumor (continued). "Furthermore, genetic or pharmacologic targeting of USP28 recapitulated the genetic depletion of the master SCC transcription factor ∆Np63 and showed a high overlap with regard to essential biological processes essential to SCC tumours." (PMID 32128997, 2020). "In the intestine, USP28 deletion does not affect FBW7 stability and attenuates tumorigenesis, while in tissues where FBW7 autocatalytic turnover is favored, deletion of USP28 resembles FBW7 loss-of-function, thus exhibiting a tumor-promoting effect." (PMID 29415985, 2018). "Furthermore, inhibition of USP28 via a small‐molecule inhibitor resets the proteome of transformed cells towards a ‘premalignant’ state, and its inhibition synergizes with clinically established compounds used to target EGFRL858R‐, BRAFV600E‐ or PI3KH1047R‐driven tumour cells." (PMID 35364627, 2022). "This revealed that USP28, SREBP2 and HMGCS1, but not SREBP1, were significantly higher expressed in LSCC tumours (n = 33) compared to LADC tumours (n = 75)." (PMID 37202505, 2023). "This was further validated by immunostaining of nontransformed versus tumour samples from NSCLC patients, where a significant increase in USP28 protein abundance was detected already at low‐grade stages for lung ADC and SCC." (PMID 35364627, 2022). "It is noteworthy that the USP28 targets c‐JUN and c‐MYC were not downregulated in established tumours in KPLU mice, when compared to KPL." (PMID 32128997, 2020). "Similar to USP28, it is not clear if UBR5 functions as an oncoprotein or a tumor suppressor." (PMID 34685632, 2021).
adenocarcinoma (3 papers, 2016 to 2022). A common cancer characterized by the presence of malignant glandular cells. "USP28 is rarely lost or mutated, but frequently transcriptionally upregulated in human SCC compared to healthy lung tissue or ADC (adenocarcinoma) patient samples (and EV1A and B)." (PMID 32128997, 2020). "Notably, inhibition of USP28 in human adenocarcinoma cell lines, and in the SCC line SiHa, which does not express ∆Np63, led to a reduction of ɣ-H2AX, and co-treatment with cisplatin had no additive nor synergistic effect." (PMID 34611298, 2022).
cardiovascular disease (2 papers, 2024 to 2025). "Recent studies have highlighted the involvement of DUBs such as USP25, JOSD2, and USP28 in cardiovascular diseases." (PMID 40192103, 2025).
infection (2 papers, 2022 to 2024). The state of being infected such as from the introduction of a foreign agent such as serum, vaccine, antigenic substance or organism. "While the loss of Plk4 did not significantly affect IgM immunoglobulin levels, representing largely natural antibodies that are produced in the absence of infection, IgG1 levels clearly dropped in Plk4 mutant mice, but were back to normal when Usp28 was co-deleted and B cell maturation restored." (PMID 39406735, 2024).
heart diseases (1 paper, 2024). "Therefore, the clinical application of USP28 inhibitors should be cautious and depend on the diagnosis of specific heart diseases." (PMID 39431010, 2024).
immune system diseases (1 paper, 2024). "USP28 has been reported to be up-regulated in neurodegenerative diseases 11, a variety of tumors 12, and immune system diseases 13, and knockout or inhibition of USP28 can effectively mitigate these diseases 11-13, suggesting the potential of USP28 as a drug target." (PMID 39431010, 2024).
USP28 also shares sentences with these, for which no sentence is quoted: diabetic cardiomyopathy (2 papers); intestinal cancer (2); invasive ductal breast carcinoma (2); lung (2); lymph node metastasis (2); stomach cancer (2); Ataxia (1); breast tumors (1); cervical cancer (1); colorectal tumour (1); endocervical adenocarcinoma (1); gastrointestinal disease (1); head and neck squamous cell carcinoma (1); Hyperglycemia (1); hypertrophic cardiomyopathy (1); hypertrophy (1); inflammation (1); leukemia (1); metabolic disease (1); neurodegenerative disease (1); retinopathy (1); skin cancer (1); thyroid cancer (1).